LINC02159 (long independently transcribed non-coding RNA 2159)
Gene: Long non-coding RNA gene on chromosome 5 (160,931,778 to 160,938,626, reverse strand). Ensembl gene ENSG00000253417.
Diseases named in the same sentence as LINC02159 in open-access papers:
LINC02159 is named in the same sentence as 4 diseases in open-access papers, as found by Europe PMC text mining. Sharing a sentence is not in itself a finding about the gene and the disease. The quoted sentences say what the papers report.
colorectal cancer (1 paper, 2025). A primary or metastatic malignant neoplasm that affects the colon or rectum. "Furthermore, MRTX1133 suppresses progression of KRAS G12D-mutated colorectal cancer by inducing ferroptosis via the METTL14/LINC02159/FOXC2 axis." (PMID 40746552, 2025).
hepatocellular carcinoma (1 paper, 2025). A malignant tumor that arises from hepatocytes. "Notably, LINC02159 functions as a dangerous factor and a hub cytokine in hepatocellular carcinoma development and the prognosis network, inspiring us to further elucidate the mechanism of LINC02159 in NSCLC." (PMID 40798857, 2025).
cancer (2 papers, 2023 to 2024). A tumor composed of atypical neoplastic, often pleomorphic cells that invade other tissues. "Interestingly, an examination of the GTEx database revealed that despite its upregulation in cancer tissues, higher LINC02159 expression was significantly associated with better overall survival and disease-free survival in CRC patients." (PMID 39657309, 2024). "We discovered that LINC02159 was highly correlated with cancer growth and metastasis-related pathways by using transcriptomic analysis and that YAP1 was a potential target gene of LINC02159." (PMID 37537569, 2023).
tumor (2 papers, 2023 to 2024). "Collectively, these findings reveal a complex role of LINC02159 in CRC: while it is upregulated in CRC tissues, higher expression levels correlate with better patient outcomes, suggesting that LINC02159 may serve as a compensatory tumour suppressor specifically in KRASG12D mutated CRC." (PMID 39657309, 2024). "In vitro and in vivo experiments suggest that LINC02159 acts as a tumour suppressor in CRC progression." (PMID 39657309, 2024). "In vitro and in vivo experiments suggested that LINC02159 acts as a tumour suppressor in CRC progression." (PMID 39657309, 2024). "We further analyzed LINC02159 expression by using TCGA data and the results also showed an upregulation of LINC02159 in tumor tissues of NSCLC patients." (PMID 37537569, 2023). "Notably, LINC02159 expression is downregulated in KRASG12D-mutant CRC cells, thereby compromising its tumour-suppressive function." (PMID 39657309, 2024).